CHEK2 (checkpoint kinase 2)
Diseases named in the same sentence as CHEK2 in open-access papers (continued):
Sharing a sentence is not in itself a finding about the gene and the disease.
breast cancer (continued). "Sequencing of the CHEK2 gene in 25 breast cancer patients and 25 healthy controls, from the French Canadian population did not reveal any pathogenic mutations." (PMID 18706089, 2008). "To search for potential interactions between the products of these breast cancer susceptibility genes, we undertook systematic mapping of BRCA2 for potential phosphorylation sites by CHEK2." (PMID 18797466, 2008). "Mutations in ATM, BRIP1, PALB2, CHEK2 and possibly NBS1, RAD50 are also associated with a moderately increased risk for breast cancer, and many low penetrance genes have recently been identified." (PMID 18706089, 2008). "The highest prevalence of CHEK2 1100delC has been reported in familial non-BRCA1/2 families also harboring colon cancer cases (18%) and in some highly selected high-risk breast cancer families (9–11%)." (PMID 17705858, 2007). "Mutation frequencies reported in the literature indicate that about 10% of all women with breast cancer diagnosed before the age of 50 years have a germline mutation in BRCA1, BRCA2, ATM or CHEK2." (PMID 17428320, 2007). "We analyzed the prevalence of CHEK2 1100delC in 763 breast cancer patients with a defined family history and 760 controls from the Stockholm region." (PMID 17705858, 2007). "We then assessed the association of the tagSNPs in the ATM, CHEK2 and ERBB2 genes and their haplotypes with breast cancer survival and the risk of tumour-characteristic-defined breast cancer." (PMID 17132159, 2006). "We calculated global P values for the association between the tagSNP haplotypes in the ATM, CHEK2 and ERBB2 genes and the risk of tumour-characteristic-defined breast cancer from logistic regression models." (PMID 17132159, 2006). "Until now, common variation in the ATM, CHEK2 and ERBB2 genes has mainly been studied in relation to the overall risk of breast cancer, but the results have been inconclusive." (PMID 17132159, 2006). "We estimated the risk of death from breast cancer associated with the tagSNPs in the ATM, CHEK2 and ERBB2 genes or their haplotypes." (PMID 17132159, 2006). "Our data did not support an association between common variation in the ATM, CHEK2 and ERBB2 genes and breast cancer survival or the risk of developing tumours of different characteristics." (PMID 17132159, 2006). "Background/Objectives: Contralateral breast cancer (CBC) is a significant concern among breast cancer survivors, particularly in those with moderator-high penetrance germline mutations such as BRCA1, BRCA2, CHEK2, and ATM." (PMID 41976331, 2026). "Compared to female breast cancer (FBC), MBC shows a higher prevalence of hormone receptor positivity and distinct germline predispositions, most frequently pathogenic variants in BRCA2 and CHEK2." (PMID 41919251, 2026). "Furthermore, CHEK2 c.1100delC breast cancer patients were diagnosed with smaller tumors (67.3 % vs 55.0 % of tumors ≤2 cm) but more often lymph node positive disease (44.3 % vs 30.9) compared to non-carriers." (PMID 41314031, 2025).
breast cancer (continued). "The majority of the studies included Dutch CHEK2 c.1100delC breast cancer patients." (PMID 41314031, 2025). "Although several studies have individually explored the roles of XRCC1 (rs1799782), CHEK2 (rs17879961), and XPD (rs238406) in cancer risk, few have evaluated their combined interaction or distribution across breast cancer subtypes in a clinically annotated patient population." (PMID 40507526, 2025). "For both PALB2 and CHEK2, a high PRS was associated with an increased risk of breast cancer." (PMID 40227593, 2025). "In this cohort study, the CHEK2 LR variants p.I157T, p.S428F, and p.T476M were associated with cancer, multiple primary cancers, breast cancer, and bilateral breast cancer when found in combination with a PV, but not in the biallelic state." (PMID 39745704, 2025). "The odds ratio for a CHEK2 mutation was higher for cases with a positive family history (OR = 2.3, 95%CI 1.3–3.9, p = 0.003) than those with no family history of breast cancer (OR = 1.4, 95%CI 0.96–2.1, p = 0.06)." (PMID 40770660, 2025). "Interestingly, for PALB2, the risk of CBC was increased if the primary breast cancer was ER-negative (HR 2.9; 95% CI 1.4–6.4; p = 0.006), whereas it was increased for CHEK2 if the primary breast cancer was ER-positive (HR 2.0; 95% CI 1.1–3.5; p = 0.02)." (PMID 39858629, 2025). "Only CHEK2 mutations predisposed to DCIS, therefore we investigated their influence on age of DCIS diagnosis, the impact on survival among patients, and the effect of positive family history of breast cancer in CHEK2 carriers on the risk of DCIS." (PMID 40770660, 2025). "The results suggested that annual MRI screening from 30 to 35 years, followed by annual mammography at 40 years, might reduce breast cancer mortality by over 50% for women with ATM, CHEK2, and PALB2 P/LP variants." (PMID 39858629, 2025). "Although our results differ from previous studies in CHEK2 c.1100delC breast cancer patients, one recent study in breast cancer patients with any (likely) pathogenic CHEK2 variants also showed a similar breast cancer-specific survival in heterozygotes and non-carriers." (PMID 41314031, 2025). "Another study indicated that the estimated lifetime breast cancer risk for BRCA1 and BRCA2 PV carriers increased with higher PRS313 scores, though the observed effect was smaller than in the general population or among carriers of PVs in ATM, CHEK2, and PALB2." (PMID 40296163, 2025). "Increased risks of second (contralateral) breast cancer diagnosis have been described for CHEK2 c.1100delC breast cancer patients [,11], and could therefore have been a reason for the increased risk of recurrent disease reported previously." (PMID 41314031, 2025). "In CHEK2 carriers with no affected relatives, the risk of breast cancer was approximately 20%, increasing to 44% when both first- and second-degree relatives were affected." (PMID 39858629, 2025).
breast cancer (continued). "Of note, LOH of the remaining CHEK2 allele is also not always observed in breast cancers with confirmed germline CHEK2 variants." (PMID 38898688, 2024). "•Lifetime breast cancer risk in unaffected CHEK2 heterozygotes and familial non-carriers was calculated using CanRisk." (PMID 38039887, 2024). "The present study pioneered the acquisition of the mutational landscape of the breast cancer susceptibility genes (ATM, CHEK2, PALB2, and XRCC2) using next-generation whole-exome sequencing from paraffin-fixed FFPE tissue blocks obtained from the breast cancer patients of Pashtun ethnicity." (PMID 38784039, 2024). "Similarly, in a study that included 65,057 women with breast cancer, the age of diagnosis of CHEK2 PV’s carriers was 47.7 years." (PMID 38929805, 2024). "Many pathogenic gene mutations common to breast cancer, such as Pten, Brca2, Atm, Cdh1, Chek2, Nf1, Arid1a, Pik3ca, and Esr1, revealed no alterations between NT2.5 and NT2.5-LM." (PMID 38717519, 2024). "Besides, rare variants in other genes like ATM, CHEK2, CDH1, PALB2, RAD50, and RAD51C have been detected mainly in the breast cancer subgroup." (PMID 39148954, 2024). "Findings from our study showed that females with the CHEK2 I157T GPV have similar cancer risk management practices as those with the CHEK2 1100delC GPV despite lower breast cancer risks that do not reach the threshold for high-risk breast cancer screening." (PMID 39062660, 2024). "CHEK2 p.R180C has been reported in breast cancer of familial nature in German and Jewish ethnicity." (PMID 38784039, 2024). "Considering breast cancer-associated mutations across a broader range of genes (BRCA1, BRCA2, PALB2, and the more moderate-risk genes, ATM and CHEK2), the average carrier risk is equivalent to the top 3% of the PRS distribution (see S1 File for definition of mutation carriers)." (PMID 39292644, 2024). "At the variant level, there were no common VUS among these breast cancer groups, except for CHEK2 c.1427C > T (classified as a risk factor) and CHEK2 c.549G > C (VUS)." (PMID 38308423, 2024). "Moreover, women with a pLOF in ATM or CHEK2 and ranking in the top 50% of the PRS displayed a high risk (39.2% probability of breast cancer at age 70), whereas their counterparts in the bottom 50% of the PRS were not at high risk (14.4% probability at age 70)." (PMID 39669587, 2024). "Oophorectomy has been shown to diminish breast cancer mortality in carriers of BRCA1, BRCA2 and CHEK2 mutation mutations but has not yet been studied in breast cancer patients with ATM mutations." (PMID 39543654, 2024). "In cells grown in 3D, progestins regulate a group of breast cancer-associated genes that are also regulated in 2D including CDH10, PGR, CHEK2, LSP1, TERT, SDPR, but also a new set of 3D-exclusive genes, associated to the ECM including members of the integrin family, Laminins, and AKT3." (PMID 38565950, 2024). "PVs in BRCA1, BRCA2, CHEK2, and ATM increase the lifetime cancer risk of breast cancer." (PMID 38929805, 2024). "Cancers from individuals heterozygous for CHEK2 gPVs also presented with tissue-specific mutational signatures in 10/28 (36%) cancers, including mutational signatures SBS2 and SBS13 in bladder and breast cancers, and mutational signature SBS29 (tobacco chewing) in lung cancers." (PMID 38848470, 2024). "In one case, there is likely only a manifestation of the CHEK2 spectrum with colorectal cancer, and the appearance of bladder cancer as a second primary in one of the breast cancer patients could be considered an atypical manifestation." (PMID 39021548, 2024). "Moreover, c.6115G>A in ATM and c.592+3A>T in CHEK2 were of keen interest identified in families with multiple breast cancer cases and their familial cosegregation with disease has been also confirmed." (PMID 38313678, 2024).
breast cancer (continued). "Here, we show that both breast and non-breast cancers from individuals who have biallelic gPVs in CHEK2 (germline CHEK2 deficiency) do not present with molecular profiles that fit with HRR deficiency." (PMID 38848470, 2024). "Mutation spectrum of ATM, CHEK2, PALB2, and XRCC2 genes in patients with breast cancer." (PMID 38784039, 2024). "Germline CHEK2 variants have now been identified in ~ 1% of the population, and pathogenic variants (PVs) are causally linked to multiple types of cancer, including colon cancer and breast cancer (BC), further highlighting the functional relevance of CHEK2 in safeguarding genome integrity." (PMID 38091153, 2024). "An alternative approach (strategy #2) could entail discontinuing the ascertainment of family history of breast cancer and instead refer all women with a pathogenic variant in BRCA1, BRCA2, PALB2, ATM, and CHEK2 or a PRS in the top 10%." (PMID 39669587, 2024). "Firstly, overrepresentation analysis highlighted a connection to breast cancer (BC) that was supported by the CHEK2 GPV enrichment in early-onset OC(p = 1.2 × 10–4), and the presumably BC-specific PRS313, which successfully stratified early-onset OC-patients from controls(p = 0.03)." (PMID 39003285, 2024). "High risk of breast cancer development is observed in individuals carrying CHEK2 gene variants especially in the context of family history of breast cancer, which is clearly demonstrated in the pedigree of our patient with a VUS in the CHEK2 gene." (PMID 37277882, 2023). "Among 104 breast cancer patients with thyroid cancer in relatives, the frequency of CHEK2 mutation was higher than in the group of breast cancer patients without thyroid cancer in probands or relatives (11,5% vs 8,5%)." (PMID 37434214, 2023). "The baseline frequency of all 4,436 CHEK2 VUS carriers was significantly higher in patients over controls [3.4% vs. 2.3%; OR, 1.52; 95% confidence interval (CI), 1.43–1.61] setting a low but significant background breast cancer risk." (PMID 37449874, 2023). "For this purpose, here we have tested the prevalence of CHEK2 p.(Asp438Tyr) in breast cancer patients with the indication of hereditary disease susceptibility and those unselected for the family history of cancer and age at disease onset, all collected from the North Ostrobothnia area." (PMID 36653541, 2023). "Breast cancer family history was not strongly associated with CHEK2 or ATM PV status among unaffected women." (PMID 37084156, 2023). "Recently published studies assessing the clinical validity of genes frequently tested in hereditary breast and ovarian cancer mostly agree that ATM, BRCA1, BRCA2, CHEK2, and PALB2 are strongly associated with a risk of breast cancer (overall with a p value of less than 0.0001)." (PMID 37239898, 2023). "Because CHEK2*1100delC mice have indolent tumorigenesis and only a small proportion present with mammary tumors, we next examined evolution of preneoplastic lesions in a mammary tumor susceptible transgenic mouse model (MMTV-Ron kinase) crossed into the CHEK2*1100delC line." (PMID 37390209, 2023). "Pathogenic variants detected in other breast cancer susceptibility genes, such as ATM, CHEK2, PALB2, RAD51, and BARD, may also explain a proportion of the genetic risk." (PMID 37239898, 2023). "We next tested whether germline mutations in CHEK2 alter PR positivity, because ER+/HER2− tumors can be either PR+ (strongly driven by ER signaling) or PR− constituting distinct breast cancer subtypes that coincide with Luminal A and B subtypes, respectively." (PMID 37390209, 2023).
breast cancer (continued). "Moreover, next-generation sequencing revealed that beyond BRCA1/2, mutations in homologous recombination effectors, such as PALB2, RAD51, ATM, BRIP1, BARD1, and CHEK2 also occur in breast cancer." (PMID 36613148, 2023). "Our results indicate that CHEK2 p.(Asp438Tyr) carriers do not have an increased risk for breast cancer and the classification of the CHEK2 p.(Asp438Tyr) variant can be changed from the variant of uncertain significance (VUS) to likely benign for breast cancer." (PMID 36653541, 2023). "Previously, we have identified pathogenic mutations of BRCA1, BRCA2, CHEK2, and PALB2 in about half of 1018 Polish families with hereditary breast cancer, and we have observed that 18 founder mutations are responsible for about 80% of all the mutations detected in these genes." (PMID 37510234, 2023). "The estimated lifetime risk of acquiring breast cancer with an ATM, CHEK2, PALB2 mutation is greater than 20% which is considered a “moderate risk” compared to the effects of the pathogenic variants in BRCA1 and BRCA2 genes with a lifetime risk of approximately 50%." (PMID 37239898, 2023). "While early age at diagnosis was strongly associated with BRCA1 and modestly with BRCA2, it was associated with only a very modestly (ATM and CHEK2) or no (PALB2) increased risk of carrying a PV in non-BRCA1/2 breast cancer-associated genes." (PMID 37084156, 2023). "In addition to BRCA1 and BCRA2 genes, other genes, such as CHEK2, PALB2, and PTEN, are less common but also confer an elevated risk of breast cancer among men." (PMID 38146568, 2023). "The CHEK2 and ATM genes are known to be implicated in the development of breast cancer, but the exact association is not clearly understood, and insufficient data are published about the variants classified as having “unknown significance” in these genes." (PMID 37239898, 2023). "The mutations in the CHEK2 gene were already reported to correlate with the risk of prostate and breast cancer, but not with ovarian cancer." (PMID 35313928, 2022). "For women with other HOC mutations associated with significant breast cancer risk such as CHEK2, PALB2 and ATM, the impact of RRBSO on breast cancer risk remains unknown." (PMID 35159349, 2022). "The CHEK2 region (OR 1.94, p = 0.0003) covers the whole gene but nearly all the calls correspond to a deletion of exons nine and ten, which was previously observed in 1% of breast cancer cases and 0.4% of controls in Poland17." (PMID 35042965, 2022). "CHEK2 was not included in the initial germline sequencing analyses, since at that time CHEK2 was not yet recognized as a (breast) cancer-associated gene." (PMID 35053600, 2022). "Currently, approximately 40% of familial breast cancer risk is explained by a combination of common low-penetrance variants, together with coding rarer variants in predisposition genes, such as BRCA1, BRCA2, PALB2, ATM, and CHEK2 that confer higher risks." (PMID 35884425, 2022). "We also did not disclose variants for CHEK2-associated susceptibility to breast cancer (two UFs) because no national screening programs have been established for this condition in absence of familial breast cancer." (PMID 34697415, 2022). "The aim of the study is to compare the outcomes of implant and synthetic TIGR mesh-based breast reconstructions in breast cancer patients and women, who have higher lifetime risk for breast cancer, with mutated (changed) copy of genes: BRCA1, BRCA2, PALB2 or CHEK2." (PMID 35804960, 2022).